PNLIP (pancreatic lipase)
Description:
Plays an important role in fat metabolism. It preferentially splits the esters of long-chain fatty acids at positions 1 and 3, producing mainly 2-monoacylglycerol and free fatty acids, and shows considerably higher activity against insoluble emulsified substrates than against soluble ones.
Synonyms: PL; PTL; PNLIPD
Tractability: Small molecule: an approved drug acts on it; a structure with a bound ligand is known; a high-quality ligand is known; it belongs to a druggable protein family. Antibody: UniProt places it where antibodies can reach, with high confidence; its Gene Ontology location is reachable by antibodies, with high confidence; UniProt predicts a signal peptide or a membrane-spanning region. PROTAC: a small molecule that binds it is known.
Target class: Enzyme; Hydrolase
Gene: Protein-coding gene on chromosome 10 (116,545,931 to 116,567,855, forward strand). Ensembl gene ENSG00000175535.
Subcellular location: Secreted
Pathways (Reactome):
Developmental Biology: Developmental Lineage of Pancreatic Acinar Cells
Digestion and absorption: Digestion of dietary lipid
Sensory Perception: Retinoid metabolism and transport
Gene Ontology:
Molecular function: all-trans-retinyl-palmitate hydrolase, all-trans-retinol forming activity; lipase activity; triacylglycerol lipase activity; lipoprotein lipase activity; phospholipase A1 activity; retinyl-palmitate esterase activity; carboxylic ester hydrolase activity; diacylglycerol lipase activity
Biological process: lipid metabolic process; positive regulation of triglyceride lipase activity; cholesterol homeostasis; fatty acid biosynthetic process; high-density lipoprotein particle remodeling; lipid digestion; retinoid metabolic process; triglyceride catabolic process; retinol metabolic process
Cellular component: extracellular region
Genetic constraint (gnomAD): Loss-of-function variants: 27 observed, 37.85 expected, observed/expected ratio (o/e) 0.71, 90% interval 0.52 to 0.98. The upper end of that interval is the gene's LOEUF score, 0.98, which puts it in group 4 of 6, group 1 being the genes least tolerant of losing a copy. Missense variants: 370 observed, 438.54 expected, observed/expected ratio (o/e) 0.84, 90% interval 0.77 to 0.92. Synonymous variants: 152 observed, 152.71 expected, observed/expected ratio (o/e) 1, 90% interval 0.87 to 1.14.
Homologues: Orthologues: chimpanzee PNLIP (99% identical), macaque PNLIP (88% identical), pig PNLIP (82% identical), rat Pnlip (79% identical), mouse Pnlip (78% identical), rabbit PNLIP (75% identical), guinea pig PNLIP (69% identical), Drosophila melanogaster CG6847 (27% identical), zebrafish lipib (26% identical), Drosophila melanogaster CG13282 (25% identical), Drosophila melanogaster CG7367 (25% identical), Drosophila melanogaster CG34447 (24% identical), and 22 more. Paralogues in human: PNLIPRP1 (68% identical), PNLIPRP2 (63% identical), PNLIPRP3 (47% identical), LIPC (30% identical), LIPG (30% identical), LIPH (29% identical), LIPI (28% identical), LPL (27% identical), PLA1A (25% identical).
Diseases named in the same sentence as PNLIP in open-access papers:
PNLIP is named in the same sentence as 79 diseases in open-access papers, as found by Europe PMC text mining. Sharing a sentence is not in itself a finding about the gene and the disease. The quoted sentences say what the papers report.
Obesity (288 papers, 2005 to 2026). Accumulation of substantial excess body fat. "Orlistat is a well-researched pancreatic lipase inhibitor recognized for its weight reduction capabilities and positive impact on cardiovascular risk markers in patients with obesity." (PMID 40016558, 2025). "Inhibiting pancreatic lipase, associated with fat uptake in the small intestinal tract, is one way to treat obesity." (PMID 41300115, 2025). "The broad proteolytic activity of Alcalase® likely generates bioactive peptides with enhanced affinity for pancreatic lipase, aligning with previous reports that associate Alcalase®-mediated hydrolysis with anti-obesity properties in protein hydrolysates." (PMID 41149595, 2025). "These extracts and compounds have shown potential in inhibiting pancreatic lipase and other markers associated with obesity." (PMID 40509279, 2025). "Recent research efforts have concentrated on the development and assessment of inhibitors of pancreatic lipase as a strategy for addressing obesity, especially when linked to diets rich in fats." (PMID 40016558, 2025). "Saponins in American ginseng and ginseng can inhibit pancreatic lipase activity and reduce body weight, adipose tissue weight, and blood lipids of high-fat diet mice, thereby controlling obesity caused by high-fat diet." (PMID 39301282, 2024). "Another highly interesting activity that will be studied is the inhibition of pancreatic lipase, which is related to the hypocholesterolemic and anti-obesity effects associated with saponins." (PMID 38254575, 2024). "The results are further corroborated by another study that investigated the inhibitory effects of organic and aqueous extracts from Hibiscus sabdariffa on digestive enzymes associated with obesity, such as α-amylase, α-glucosidase, and pancreatic lipase." (PMID 37835351, 2023). "The molecular docking assay focuses on specific receptors such as human inducible nitric oxide synthase (iNOS), human pancreatic lipase, human reactive oxygen species (ROS) 1 kinase, and fat mass and obesity-associated (FTO) proteins." (PMID 37764670, 2023). "The inhibition of pancreatic lipase is considered a precious approach for the management of diet-induced hyperglycemia (one of causes of diabetes mellitus) and obesity." (PMID 36997571, 2023). "Considering the obesity associated risks and its high prevalence in the western population, PNLIP activity inhibition resulting in reduced fat metabolism can significantly impact obesity treatment." (PMID 36232503, 2022). "Among synthetic anti-obesity drugs, orlistat (tetrahydrolipstatin), an inhibitor of pancreatic lipase (EC 3.1.1.3), is the only currently approved weight loss medicine for the long-term treatment of obesity." (PMID 35631194, 2022). "The anti-obesity effect of S. horneri is associated with the inhibition of pancreatic lipase, which leads to the suppression of intestinal lipid absorption and their subsequent accumulation in adipose tissue and liver." (PMID 33567531, 2021). "Polyphenol-rich plant foods have been reported to induce insulin-like effects and can act as good inhibitors of enzymes such as α-amylase and pancreatic lipase associated with type 2 diabetes, obesity and lipid peroxidation." (PMID 34820413, 2021). "Overall, numerous studies in the literature have dealt with plant extracts’ and pure compounds’ inhibitory activity against digestive enzymes linked to obesity and diabetes (α-amylase, α-glucosidase, and pancreatic lipase)." (PMID 32028716, 2020). "Pancreatic lipase is involved in the digestion of lipids in food, which represent one of the major causes of obesity." (PMID 32235329, 2020). "According to these findings, the anti-obesity potential observed for K. scoparia was supposed to be linked to the effectiveness of isolated compounds on pancreatic lipase activity." (PMID 27775618, 2016).
Obesity (continued). "Obesity is caused by excess caloric intake, and this can be improved by inhibiting pancreatic lipase activity and by inhibiting or delaying lipid absorption." (PMID 21660093, 2011). "Consequently, the inhibition of pancreatic lipase (PL) directly targets a root cause of obesity by reducing fat absorption at the level of digestion." (PMID 41011118, 2025). "Thus, pancreatic lipase inhibitors are candidates for medications intended to help with weight loss and help to avoid obesity." (PMID 39852154, 2025). "Pancreatic lipase closely linked to the metabolism of triglycerides as an obesity factor." (PMID 36838700, 2023). "The pancreatic lipase enzyme plays a pivotal role in the metabolism of dietary fat and impedes its absorption through the small intestine, thereby exerting a direct impact on the underlying cause of obesity." (PMID 37999391, 2023). "Similarly, pharmacologic inhibition of pancreatic lipase is a common and approved strategy to reverse obesity, resulting in body weight loss in humans." (PMID 36835060, 2023). "In the case of obesity, overnutrition causes an alteration in the hepatic fatty acid metabolism, over-stimulating the activity of the pancreatic lipase, thereby causing a high level of triglycerides to be accumulated within the non-adipose organs, such as the liver." (PMID 37627544, 2023). "Overall, this study provides evidence that F. vesiculosus phlorotannin-rich extracts hold potential for the management of the activity of α-glucosidase, α-amylase and pancreatic lipase, which are well known to be linked to metabolic disorders such as diabetes and obesity." (PMID 30857204, 2019). "Obesity is associated with lipid metabolism involving pancreatic lipase enzyme." (PMID 28774309, 2017). "This study provides the first report of the development of anti-lipase IgY and the direct evidence that inhibition of pancreatic lipase using Anti-lipase IgY is an effective anti-obesity treatment due to the associated increase in fecal excretion of triglyceride." (PMID 24321125, 2013). "Obesity is a huge burden on social costs and is linked to many chronic diseases and cancer, Pancreatic triacylglycerol lipase (PNLIP) are the primary lipases secreted by the pancreas, and is responsible for breaking down dietary lipids into unesterified fatty acids (FAs) and monoglycerides (MGs)." (PMID 22970152, 2012). "Moreover, pancreatic lipase is the most important enzyme for the hydrolysis of dietary fat, and alterations in its expression are closely associated with metabolic diseases such as obesity." (PMID 38027005, 2023). "As the research for anti-obesity drugs is ongoing, it is possible that better knowledge about the types and locations of causative congenital deleterious PNLIP gene mutations might aid in designing and targeting critical domains of PNLIP." (PMID 24262094, 2014). "Functional assays revealed strong anti-obesity potential, with crude extracts exhibiting superior α-glucosidase inhibition (up to 98.75%), while tannin-enriched extracts showed enhanced pancreatic lipase inhibition (up to 46.26%)." (PMID 42280093, 2026). "Obesity is a worldwide problem, and lowering pancreatic lipase (PL) activity is an effective strategy to counteract it." (PMID 41008249, 2025). "In contrast, the acidic extract adjusted to pH 9 can be considered a strong radical scavenger and a favorable anti-obesity agent in terms of pancreatic lipase and α-amylase inhibition." (PMID 39852537, 2025). "Within this myriad strategy, our study offers a discussion on inhibiting pancreatic lipase (PL), which is a proven strategy for tackling obesity." (PMID 40016558, 2025). "Several synthetic anti-obesity drugs are commercially available, such as orlistat, phentermine/topiramate, liraglutide, and naltrexone/bupropion, which were developed based on pancreatic lipase inhibition." (PMID 41154479, 2025).
Obesity (continued). "For instance, bioactive compounds such as polyphenols have demonstrated effective inhibition of pancreatic lipase, highlighting their potential role in natural therapies for obesity and other metabolic disorders." (PMID 40509279, 2025). "While the general anti-obesity potential of Ɛ-viniferin has been explored in previous studies, its specific role as pancreatic lipase (PL) inhibitors remains relatively under-investigated." (PMID 41011118, 2025). "Another enzyme that is of great importance to obesity is pancreatic lipase, which breaks down lipids—mainly dietary triacylglycerides—to monoglycerides and free fatty acids, which can be easily absorbed into the circulatory system." (PMID 40363834, 2025). "This manuscript aims to explore the significance of pancreatic lipase inhibition in obesity treatment, providing an overview of current insights and future directions." (PMID 40016558, 2025). "By inhibiting pancreatic lipase, triglyceride hydrolysis is reduced, potentially decreasing the prevalence of obesity." (PMID 39852154, 2025). "The focus was on evaluating their ability to inhibit key digestive enzymes relevant to T2DM (α-amylase, α-glucosidase, sucrase, maltase) and obesity (pancreatic lipase)." (PMID 40076378, 2025). "At its core, investigating the role of pancreatic lipase in addressing obesity is a dynamic and hopeful field of inquiry." (PMID 40016558, 2025). "The inhibitory potential of the two seed extracts on three key enzymes affecting diabetes and obesity—α-amylase, α-glucosidase, and pancreatic lipase—was studied." (PMID 40363834, 2025). "Orlistat is an FDA-approved medication for obesity management that functions as a pancreatic lipase inhibitor." (PMID 40255727, 2025). "Recent studies have highlighted the potential of natural substances in offering alternative treatments for obesity by focusing on their capacity to inhibit pancreatic lipase among other pathways." (PMID 40016558, 2025). "Pancreatic lipase inhibitors, a category of medications aimed at obesity treatment, inhibit the pancreatic lipase enzyme." (PMID 40016558, 2025). "It is a complex chronic disease treated with various methods; common anti-obesity drugs include orlistat, which inhibits pancreatic lipase to reduce fat absorption, and sibutramine, which suppresses appetite and increases energy expenditure." (PMID 40283996, 2025). "For example, citrus peel extracts, which are rich in phenolic constituents, have shown effectiveness in inhibiting pancreatic lipase, suggesting their possible importance for obesity management." (PMID 40648014, 2025). "The anti-obesity effects of these compounds have been demonstrated to result from their inhibition of pancreatic lipase, in addition to their influence on the expression and secretion of various markers associated with different signaling pathways." (PMID 40509279, 2025). "Specifically, we have incorporated pancreatic lipase, one of the main target enzymes in the treatment of obesity, in eutectogels via UV-induced radical polymerization of suitable precursors in appropriate DESs." (PMID 41002354, 2025). "Orlistat, the only FDA-approved pancreatic lipase (PL) inhibitor for long-term use, has been widely used as an anti-obesity drug in the U.S. and Europe for over a decade." (PMID 40016558, 2025). "In this context, examining pancreatic lipase's contribution to obesity management unveils a fertile ground for innovation in therapeutic methods." (PMID 40016558, 2025). "High inhibitory activity exhibited by pecan nuts towards α-amylase (>60%), pancreatic lipase (69%) and especially α-glucosidase (99%) implies their antidiabetic and anti-obesity activity." (PMID 41464898, 2025). "AqLs also exhibited pancreatic lipase inhibition, suggesting potential applications in managing obesity and dyslipidemia." (PMID 40548186, 2025).
Obesity (continued). "The ACH showed potential as an anti-obesity and anti-diabetic agent by inhibiting pancreatic lipase by up to 43.4% at 0.063 mg/mL, α-amylase by up to 70% at 7.0 mg/mL and α-glucosidase by up to 67.6% at 100 mg/mL, respectively." (PMID 41300115, 2025). "This reference inhibitor is a Food and Drug Administration (FDA) and European Medicines Agency (EMA)-approved reference medication against obesity that inhibits pancreatic lipase." (PMID 41134486, 2025). "The most extensively studied approach in the search for novel anti-obesity agents focuses on the inhibition of pancreatic lipase activity, due to the scarcity of compounds that directly interact with this enzyme." (PMID 40509279, 2025). "This is the first report on bee pollen’s ability to inhibit pancreatic lipase in relation to its in vitro anti-obesity properties." (PMID 40428469, 2025). "Currently, orlistat is the only pancreatic lipase (PL) inhibitor approved for clinical use in the therapy of obesity." (PMID 41011118, 2025). "A promising strategy for developing effective anti-obesity agents is to inhibit pancreatic lipase, thereby reducing lipid absorption." (PMID 40419556, 2025). "All the generated hydrolysates possessed anti-obesity effects by inhibiting the activity of pancreatic lipase in vitro." (PMID 41154479, 2025). "This approach aims to enhance the inhibition of pancreatic lipase and other obesity-related markers, thereby improving therapeutic outcomes and reducing adverse effects associated with treatment." (PMID 40509279, 2025). "Recent studies have highly investigated alternatives to current anti-obesity treatments, targeting natural inhibitors of pancreatic lipase, a key enzyme in the digestion of dietary fats." (PMID 40016558, 2025). "In summary, focusing on pancreatic lipase as a method for treating obesity presents a promising path for crafting impactful therapeutic options." (PMID 40016558, 2025). "Polyphenols derived from rice anthocyanins and adzuki bean coat have been shown to improve lipid profiles in mammalian cells and exert a synergistic inhibitory effect on pancreatic lipase, a key enzyme involved in lipid hydrolysis related to obesity." (PMID 40904782, 2025). "The previous study explores the potential of natural peptides as inhibitors of pancreatic lipase, aiming to contribute to obesity treatment." (PMID 40016558, 2025). "By reducing fat absorption, pancreatic lipase (PL), an essential enzyme involved in the hydrolysis of triglycerides in the digestive system, can reduce obesity." (PMID 38601970, 2024). "Previous studies have found that treatments that have the ability to inhibit the activity of pancreatic lipase at levels similar to those reported in this study (29%), have effects in reducing obesity alterations." (PMID 38337654, 2024). "This study confirms their anti-obesity potential using computational approaches through inhibition of pancreatic lipase and paves the way for future investigations towards the development of anti-obesity drugs." (PMID 39328713, 2024). "The pancreatic lipase inhibition activity of LC bulb extract from wild and cultivated plants has been studied to explore its anti-obesity potential." (PMID 38473839, 2024). "Inhibiting the activity of pancreatic lipase and subsequently decreasing fat absorption presents a promising therapeutic strategy for addressing obesity." (PMID 38298460, 2024). "Orlistat, as an effective inhibitor of pancreatic lipase that reduces the absorption of fat by the organism, has been approved for treating obesity." (PMID 38794751, 2024). "In the assessment of anti-obesity activity, Cu-GO demonstrated the inhibition of pancreatic lipase enzyme activity, showcasing its potential as an anti-obesity agent." (PMID 38399142, 2024). "It is well established that pancreatic lipase inhibition, which lowers fat absorption, helps control obesity and hyperlipidemia." (PMID 39564001, 2024).